ENSG00000275674 (novel protein)
Gene: Protein-coding gene on chromosome 15 (90,266,317 to 90,314,499, forward strand). Ensembl gene ENSG00000275674.
Genetic constraint (gnomAD): Loss-of-function variants: 3 observed, 3.1 expected, observed/expected ratio (o/e) 0.97, 90% interval 0.42 to 1.85. That is too few expected variants to judge how well the gene tolerates losing a copy. Missense variants: 48 observed, 39.97 expected, observed/expected ratio (o/e) 1.2, 90% interval 0.95 to 1.53. Synonymous variants: 12 observed, 13.92 expected, observed/expected ratio (o/e) 0.86, 90% interval 0.55 to 1.39.